MUC4 (mucin 4, cell surface associated)
Diseases named in the same sentence as MUC4 in open-access papers (continued):
Sharing a sentence is not in itself a finding about the gene and the disease.
ovarian carcinoma (continued). "Overexpression of MUC4 mRNA has also been reported in ovarian cancer." (PMID 21521521, 2011). "MUC4 was ectopically overexpressed in SKOV3 ovarian cancer cells." (PMID 21521521, 2011). "In northern blot analysis a higher expression of MUC3 and MUC4 was reported in early stage ovarian tumor samples compared to the late stage ovarian tumor samples and it was proposed that they provided a protective function in ovarian cancer." (PMID 20034397, 2009). "Additionally, a recent study suggests the overexpression of MUC4 in ovarian carcinoma cells present in peritoneal effusions." (PMID 20034397, 2009). "An overexpression of MUC4 mRNA has also been previously reported in ovarian cancer." (PMID 18665193, 2008). "We have screened a large number of human ovarian cancer cell lines for expression of MUC4." (PMID 18665193, 2008). "MUC4 could also be used in combination with MUC16 for detection of advanced ovarian cancer." (PMID 34336844, 2021). "Furthermore, isolated circular colonies showed significant expression of cancer stem cell specific markers CD133 and ALDH1 and the self-renewal maintenance marker Shh, which concludes that MUC4 is enriching the cancer stem cell population in ovarian cancer cells." (PMID 21521521, 2011). "MUC1 and MUC4 overexpression induces the EMT in renal carcinoma and ovarian cancer via the Wnt/β-catenin pathway, whereas MUC16 knockdown induces EMT." (PMID 32825724, 2020). "For example, we reported that MUC4 mucin interacts with HER2 and stabilizes it, induce proliferation and metastasis of pancreatic and ovarian cancer cells." (PMID 26035354, 2015). "Our earlier studies have shown that MUC4, a transmembrane mucin, interacts, stabilizes and activates HER2 mediated downstream signaling in pancreatic and ovarian cancer cells." (PMID 25686822, 2015). "We have previously reported that MUC4 interacts with and stabilizes HER2, which resulted in the proliferation and metastasis of pancreatic and ovarian cancer cells." (PMID 26035354, 2015). "The localization of the MUC4 protein was observed in both the membrane and cytoplasm of SKOV3 ovarian cancer cells." (PMID 21521521, 2011). "We have further shown that MUC4 induces the epithelial to mesenchymal transition (EMT) through the upregulation of N-cadherin, and thereby induces metastasis of human ovarian cancer cells." (PMID 21521521, 2011). "Other studies from our laboratory have provided experimental evidence that the MUC4 mucin interacts with HER2 potentiates its downstream signaling and enhances the motility of ovarian cancer cells." (PMID 19014671, 2008). "In this study, we have provided experimental evidence that MUC4 interacts with HER2, potentiates its downstream signalling and enhances the motility of ovarian cancer cells." (PMID 18665193, 2008). "The future direction of these studies will be to explore the roles of MUC4 and TAG-72 in ovarian cancer stem/progenitor cells." (PMID 19014671, 2008). "While MUC1, MUC4, MUC15, MUC16, MUC17, and MUC21 are all potential candidate biomarkers for glioma, the extensive research on MUC1 and the current clinical application of MUC16 in ovarian cancer highlights their promise as therapeutics for glioma." (PMID 39767713, 2024). "Additionally, it has been found that inhibitors of FAK (focal adhesion kinase, induced by MUC4-overexpressing cells), ETaR (zibotentan), and TG2 (KCC-009) suppress EMT in ovarian cancer." (PMID 26356073, 2015). "In the case of ovarian cancer, the level of MUC4 is actually not predictive of the disease." (PMID 27829225, 2017). "In particular, a combined panel of MUC4, MUC5AC, and MUC16 may offer an effective and reliable diagnostic system and target for the management of various histological grades and types of ovarian cancer, although their biological functions are not clearly defined." (PMID 20034397, 2009).
colorectal cancer (23 papers, 2011 to 2026). A primary or metastatic malignant neoplasm that affects the colon or rectum. "An animal model study showed that mice deficient in Muc4 gene were resistant to experimental colitis and colorectal cancer linked to colitis." (PMID 38046046, 2023). "However, studies have reported the loss of MUC4 expression in the majority of colorectal cancers (CRCs)." (PMID 27551331, 2016). "Included within the upregulated genes in the concurrent mutation group were some previously linked with colorectal cancer carcinogenesis, including NFKBIZ, CCL20, LCN2, PLOD2, MUC1, and MUC4." (PMID 40757636, 2025). "Expression of MUC4 decreases in colorectal cancer (CRC); however, its functional role and implications in the intestinal pathology in CRC are not studied well." (PMID 35255004, 2022). "Other studies have shown MUC1, and MUC4 have been to promote nuclear localization of β-catenin in gastrointestinal and colorectal cancers." (PMID 35255004, 2022). "In contrast, the expression of MUC4 was lower in colorectal cancer, head and neck cancer, prostate cancer." (PMID 34336844, 2021). "In our data, we showed that colorectal cancer patients with germline MUC4 gene deletion experienced a poor clinical outcome." (PMID 33431054, 2021). "Recently, seromic profiling of colorectal cancer patients with a glycopeptide microarray identified abs to aberrant glycopeptides derived from MUC1 and MUC4 that may be of use for colorectal cancer screening." (PMID 24212946, 2011). "In colorectal carcinoma, these rates are MUC1, 24–32%; MUC2, 38%; MUC3, 74%; MUC4, 94%; MUC5AC, 34–50%; MUC6, 39%; and MUC16, 64%." (PMID 25551773, 2014). "MUC4 and MUC20 expression is increased in colorectal cancer vs normal mucosae (GSE40967, p < 0.01)." (PMID 30236127, 2018). "Moreover, our lab has showed the pro-tumorigenic role of MUC4; when MUC4 knockout mice were subjected to Azoxymethane/DSS treatment, it was observed that the presence of MUC4 led to a significant increase in colitis and colorectal cancer." (PMID 32168759, 2020). "In normal tissues and in many cancers, the MUC4 promoter is highly methylated and a moderate decrease in methylation is observed in cancer, except for a very minor increase in OSC and colorectal cancers that does not exceed 1.08-fold increase." (PMID 28978023, 2017).
colitis (18 papers, 2010 to 2025). Inflammation of the colon. "MUC4, a large transmembrane mucin, is naturally expressed in the small and large intestines and differentially expressed in colitis and colitis-associated cancer." (PMID 34966694, 2021). "In patients with UC and experimental colitis models, characterized by a thin mucin layer in association with goblet cell depletion, high expression of Muc1 and Muc4, and low expression of Muc2 and Tff3 have been reported." (PMID 33959000, 2021). "Mice deficient in MUC4 show resistance to DSS colitis and have reduced levels of pro-inflammatory cytokines compared to wild-type animals." (PMID 33013869, 2020). "During DSS colitis, Muc2 and Muc3 expression was selectively reduced in Nr2f6-deficient colonic scrapings whereas Muc1, Muc4 and Muc5ac expression was unaltered." (PMID 28779026, 2018). "Also, a recent study from our lab showed that Muc4 expression in mice led to increased susceptibility to AOM/DSS induced colitis and CRC." (PMID 27551331, 2016). "During colitis, a higher expression of Muc4 was maintained, and in addition, Cldn4, Ocln, and Jup, important tight and adherens junction components, were upregulated." (PMID 40471139, 2025). "In an acute colitis mouse model, a prophylactic MFGM treatment followed by DSS increased the gene expression of Muc2 and Muc4, which was associated with the enrichment of nine genera, including Bifidobacterium." (PMID 38612988, 2024). "Bifidobacterium breve UCC2003 was shown to increase and mucus layer generation genes including Muc2, Muc6, Muc5c, and Muc4 and Gja1 and Gjb8 in the mucosa-associated with DSS colitis." (PMID 39849930, 2024). "The expression pattern of Muc4 is not only a good example as the interaction effect, but also suggests that VA signaling in the colon is a prerequisite for the induction of Muc4 during colitis." (PMID 35458125, 2022). "In fact, Muc4−/− mice challenged with DSS colitis have been found to have higher expression of both MUC2 and MUC3 compared to wild-type mice." (PMID 33013869, 2020). "Mice that lacking MUC4 seems to form a resistance against the development of colitis and colitis-associated diseases." (PMID 34966694, 2021). "Although the mechanism behind the protective role of MUC4 deletion is unknown, it is possible that Muc4−/− mice respond by upregulating protective mucins in a compensatory manner to resist DSS-induced colitis." (PMID 33013869, 2020). "We also assessed the main secretory mucin in the gut (Muc2), and a transmembrane mucin (Muc4) on the surface of intestinal epithelial cells, considering their importance both in experimental colitis and roles in postnatal intestinal mucus layer regulation related to microbial colonization." (PMID 32711559, 2020). "Additionally, in an acute colitis prevention mouse model, prophylactic MFGM treatment resulted in an upregulation in Muc2 and Muc4 gene expression." (PMID 38612988, 2024). "Contrary, the pro-tumorigenic role of MUC4 has observed in chemical-induced colitis and CRC models and hypothesized that the tumorigenic potential of MUC4 is due to truncated glycan epitopes present on it and altered binding affinity of MUC4 antibodies." (PMID 35255004, 2022).
lung adenocarcinoma (18 papers, 2011 to 2025). A carcinoma that arises from the lung and is characterized by the presence of malignant glandular epithelial cells. "Pathway analysis showed that miR-502-3p, miR-500a-3p, and miR-652-3p (two other upregulated miRNAs in EGFR-mutated lung adenocarcinoma), interact with and downregulate MUC4." (PMID 37111289, 2023). "Downregulated MUC4 has previously been shown to promote tumor progression in EGFR-mutated lung adenocarcinoma." (PMID 37111289, 2023). "They reported the diagnostic value of MUC4 immunostaining in distinguishing mesothelioma and lung adenocarcinoma." (PMID 29317712, 2018). "In addition, high MUC4 expression was associated with poor prognosis of lung adenocarcinoma patients." (PMID 30683132, 2019). "Therefore, we evaluated the diagnostic applicability of MUC4 immunohistochemistry for differentiation of epithelioid mesothelioma to lung adenocarcinoma and squamous cell carcinoma." (PMID 29317712, 2018). "Our immunohistochemistry (IHC) studies have revealed that a high MUC1/SP-A ratio is strongly associated with a poor outcome in patients with small-size lung adenocarcinoma and that high MUC4 expression in lung adenocarcinoma patients associates with poor outcome." (PMID 28680536, 2017). "For example, MUC4 is thought to be a very specific (100%) and sensitive (91.4%) marker in paraffin-embedded lung adenocarcinoma tissue, which could be useful in diagnostic practice in the distinction between malignant mesothelioma and adenocarcinoma." (PMID 24204934, 2013). "The transcription factor PR domain containing 16 (PRDM16) was found to be downregulated in lung adenocarcinomas, which represses the transcription of Mucin‐4 (MUC4), one of the regulators of epithelial‐to‐mesenchymal transition (EMT) process of cancer cells." (PMID 36504353, 2023). "Among the candidate target genes, MUC4 was elevated in lung adenocarcinoma tissues, and its expression negatively correlated with PRDM16." (PMID 30683132, 2019). "In this study, we showed that PRDM16 functions as a transcriptional repressor of MUC4 in lung adenocarcinomas." (PMID 30683132, 2019). "Taken together, PRDM16 suppresses cancer cell EMT by downregulating MUC4 expression in lung adenocarcinoma cells." (PMID 30683132, 2019). "In this study, we analyzed the utility of MUC4 to distinguish epithelioid mesothelioma from lung adenocarcinoma and squamous cell carcinoma." (PMID 29317712, 2018). "The sensitivity, specificity, and accuracy of MUC4 are comparable to that of previously known markers of lung adenocarcinoma and squamous cell carcinoma, namely CEA, Claudin 4 and better than that of MOC-31." (PMID 29317712, 2018). "In contrast, MUC4 expression was observed in 50/60(83.3%) cases of lung adenocarcinoma and 50/56(89.3%) cases of lung squamous cell carcinoma." (PMID 29317712, 2018). "MUC4 expression was present in the cytoplasm of the tumor cell of lung adenocarcinoma and squamous cell carcinoma." (PMID 29317712, 2018). "They found that MUC4 was expressed in 0 of the 41 epithelioid mesotheliomas and 32 of the 35 (91%) lung adenocarcinoma." (PMID 29317712, 2018). "Network structural analysis provided a comprehensive view of the complex miRNA–mRNA interactions in EGFR-mutated lung adenocarcinoma, including DUSP4 and MUC4 axes." (PMID 30404194, 2018). "Our results are the first to demonstrate that TET1-mediated DNA hypomethylation regulates the expression of MUC4 in lung adenocarcinomas." (PMID 28680536, 2017). "In this study, we sought to further characterize the epigenetic changes of the MUC4 promoter region in lung adenocarcinomas through analysis of DNA samples with the MSE method (with bisulfite treatment and/or TET assisted bisulfite treatment)." (PMID 28680536, 2017). "In the present study, we analyzed the correlation between MUC4 expression and DNA methylation and 5mC and/or 5hmC scores in the promoter region of MUC4 in lung adenocarcinomas." (PMID 28680536, 2017).
lung adenocarcinoma (continued). "Recently, we have reported that the expression of MUC4 is an independent poor prognostic factor of pancreatobiliary adenocarcinomas as well as lung adenocarcinoma and oral squamous cell carcinoma." (PMID 23152882, 2012). "But only lung adenocarcinoma patients with high MUC4 expression had shorter overall survival." (PMID 30683132, 2019). "But our results in vitro showed that MUC4 promotes EMT in lung adenocarcinoma." (PMID 30683132, 2019). "However, in lung adenocarcinoma, particularly in stage 1A cases, high expression of MUC4 indicates a reduced survival rate compared to similar cases with low MUC4 expression." (PMID 27829225, 2017). "Moreover, MUC4 overexpression was found to correlate with poor prognosis in small-sized lung adenocarcinomas." (PMID 24204934, 2013). "MUC4 expression was correlated with poor prognosis in small-sized lung adenocarcinoma." (PMID 21886786, 2011). "Both in vitro and in vivo analyses established that PRDM16 was capable of inhibiting the EMT of cancer cells by repressing the transcription of Mucin-4 (MUC4), one of the regulators of EMT in lung adenocarcinomas." (PMID 32290321, 2020). "Overexpression of PRDM16 inhibited the cancer cell EMT process by suppressing the transcription of its target gene MUC4, which promoted EMT in lung adenocarcinomas." (PMID 30683132, 2019). "Overexpressing PRDM16 inhibited the epithelial-to-mesenchymal transition (EMT) of cancer cells both in vivo and in vitro by repressing the transcription of Mucin-4 (MUC4), one of the regulators of EMT in lung adenocarcinomas." (PMID 30683132, 2019). "However, the analysis results from TCGA datasets indicated that lung adenocarcinoma patients with high MUC4 expression did not significantly correlate with higher lymph node status and TNM stage grade in statistics." (PMID 30683132, 2019). "Overexpression of full-length PRDM16 or PRDM16-ΔPRD can suppress the transcription of MUC4 which is demonstrated to promote EMT in lung adenocarcinomas, suggesting full-length and PR-lacking PRDM16 exert similar effects on the metastatic ability of cancer cell in lung adenocarcinomas." (PMID 30683132, 2019). "In conclusion, MUC4 can be added as additional positive marker of non-small cell carcinoma (both lung adenocarcinoma and squamous cell carcinoma) and negative immunohistochemical marker to differentiate epithelioid mesothelioma from lung adenocarcinoma and squamous cell carcinoma." (PMID 29317712, 2018).
pancreatic ductal adenocarcinoma (17 papers, 2012 to 2025). An infiltrating adenocarcinoma that arises from the epithelial cells of the pancreas. "Mucin4 (MUC4) is highly expressed in pancreatic ductal adenocarcinoma (PDAC) while showing negligible expression in the normal pancreas, which makes the MUC4 antigen a promising target for NIR antibody labeling." (PMID 40563681, 2025). "MUC4 is the most differentially expressed gene in pancreatic ductal adenocarcinoma (PDC), and its expression level differed between each stage of cancer progression." (PMID 27829225, 2017). "Molecular mechanistic study suggest loss of cystic fibrosis transmembrane conductance regulation (CFTR) and a corresponding increase in MUC4 expression is observed in about 81% of pancreatic ductal adenocarcinoma cell lines." (PMID 24454496, 2013). "As reported in other studies, MUC4 is expressed in 83 % of pancreatic ductal adenocarcinoma samples, both poorly differentiated as well as well-differentiated types." (PMID 22537161, 2012). "In pancreatic ductal adenocarcinoma, the prevalence of MUC4 expression reached 83 to 89% of tumors." (PMID 34164227, 2018). "Although MUC4 is undetectable in normal bile duct cells, its expression is detectable in the larger bile ducts of intra- and extrahepatic cholangiocarcinomas, as well as ductal adenocarcinomas of the pancreas." (PMID 27829225, 2017). "Therefore, we presume that YY1 suppresses invasion and metastasis of pancreatic ductal adenocarcinoma by downregulating MMP10 in a MUC4/ErbB2/MEF2C-dependent mechanism." (PMID 24884523, 2014). "As far as ME2C is concerned, it demonstrated its activation by the MAPK p38 in inflammation in monocytic cells, whereas downregulation of the MUC4/ErbB2/p38/MEF2C‐dependent pathway was shown to suppress invasion and metastasis of pancreatic ductal adenocarcinoma." (PMID 31930767, 2020). "Recently, three T-cell factor/lymphoid enhancer factor (TCF/LEF)-binding sites have been identified on the MUC4 promoter, and binding of fibrotic transcription factor β-catenin/TCF4 to the MUC4 promoter has been observed in cells from pancreatic ductal adenocarcinoma, inducing its expression." (PMID 31514468, 2019). "To evaluate the relevance of our cellular model findings in human cancer, we quantified MUC4 and LGALS3 mRNA levels in the cancerous and non-tumoral areas obtained from 10 human pancreatic ductal adenocarcinomas (PDAC)." (PMID 28262838, 2017).